CTHRC1 (collagen triple helix repeat containing 1)
Diseases named in the same sentence as CTHRC1 in open-access papers (continued):
Sharing a sentence is not in itself a finding about the gene and the disease.
tumor (130 papers, 2007 to 2026). "CTHRC1 encodes a conserved, secreted glycoprotein enriched in the tumor microenvironment and secreted by both tumor and stromal cells." (PMID 40948085, 2025). "Recent studies suggest that CTHRC1 has been shown to enhance the recruitment and polarization of tumor-associated macrophages toward an M2 phenotype, which is commonly associated with immunosuppression and tumor progression." (PMID 40978044, 2025). "Increased CTHRC1 expression has consistently been associated with tumor development, and its expression level significantly correlates with the prognosis of cancer patients." (PMID 37938417, 2023). "It has been reported that CTHRC1 was associated with tumor progression and metastasis in multiple tumor types 24-29." (PMID 35664061, 2022). "CTHRC1, one of the glycosylated proteins, has been found to be elevated in multiple cancer types and linked to tumor development and metastasis." (PMID 35450397, 2022). "We found CAFs which highly expressed CTHRC1 (from F04 and F08) and tumor associated macrophages were mediated by a different set of ligand-receptor pairs, including THY1/aXb2 complex, GRN/TNFRSF1A, CD99/PILRA, CD74/MIF, APP/CD74, ANXA1/FPR1, etc." (PMID 35928443, 2022). "Gene sets associated with Gα signaling, GPCR ligand binding, neutrophil degranulation, interleukin signaling, and tumor-associated pathways showed varying degrees of enrichment in the highly expressed phenotype of the CTHRC1 gene." (PMID 35307012, 2022). "We used data from the GEPIA2 portal to determine if the change in expression of CTHRC1 and 13 hub genes is associated with tumour grade." (PMID 36190948, 2022). "We further focus on the M2 like macrophages, and we found M2 macrophages infiltration were strongly associated with CTHRC1 high expression, which provides profound insight into mechanisms governing tumor macrophages infiltration and functional activation." (PMID 35928443, 2022). "Overexpression of CTHRC1 in solid tumors leads to enhanced tumor cell migration and invasion and is associated with decreased overall survival and disease-free survival." (PMID 33505467, 2021). "According to the previous reports, the collagen triple helix repeat containing 1 (CTHRC1) causes tumorigenesis by modulating the tumor microenvironment, however, the evidence is limited to a few human cancer subtypes." (PMID 34615943, 2021). "In the upregulated pairs, the B-cell leukemogenesis gene FZD6 and its ligand CTHRC1 were upregulated in several solid tumors, associated with increased cell migration and tumor invasion." (PMID 33777800, 2021). "Further, increased CTHRC1 has been linked to the upregulation of matrix metalloproteinases (MMPs) which have established roles in tumor progression and metastasis in humans." (PMID 33717164, 2021). "CTHRC1 was elevated in some tumor tissues and associated with clinicopathological features, including late T stage, lymph nodal metastasis, and TNM staging." (PMID 33628726, 2020). "Another study demonstrated that CTHRC1 expression has a role in tumor-associated macrophages infiltration by upregulating fractalkine chemokine receptor (CX3CR1) expression." (PMID 33628726, 2020). "Another study has been reported that the CTHRC1 up regulation was significantly associated with tumor stage, differentiation, survival, prognosis, depth of invasion, lymph node involvement, and tumor size among a sub population of GC patients." (PMID 32467737, 2020). "To further understand the underlying mechanisms through which CTHRC1 promotes tumour invasion and metastasis, we performed ELISAs to detect CTHRC1 in 92 clinical NSCLC serum samples." (PMID 29631554, 2018). "In our previous study, CTHRC1 overexpression in NSCLC cells was associated with tumour aggressiveness; however, how CTHRC1 is involved in tumour cell migration and metastasis has yet to be fully elucidated." (PMID 29631554, 2018).
tumor (continued). "We detected a high CTHRC1 expression in the tumor-associated fibroblasts/activated fibroblasts and in the intimal layer of aberrantly shaped immature tumor blood vessels." (PMID 26918341, 2016). "Although the functional roles of CTHRC1 in tumor cell EMT are well established, the underlying mechanisms of how CTHRC1 regulates the EMT process are unclear." (PMID 26452130, 2015). "Collected evidence supports the idea that CTHRC1 is closely linked with tumor invasion as well as metastasis." (PMID 25238260, 2014). "Additionally, median survival increased approximately 2.5-fold in Cthrc1 KO mice, from 28 days post-inoculation in WT (n = 10) to 69 days in CTHRC1-deficient mice (n = 10), suggesting CTHRC1 promotes tumor growth within the TME." (PMID 42191349, 2026). "CTHRC1 modulates communication between tumor-associated fibroblasts and macrophages." (PMID 40134434, 2025). "This suggests that elevated CTHRC1 expression may be associated with a higher risk of HNSCC, and CTHRC1 can serve as a tumor marker to predict the risk of HNSCC occurrence." (PMID 38937712, 2024). "This alteration implies that CTHRC1 may be linked to the imbalance in macrophage proportion, a factor deemed crucial in tumor development, immune evasion, and subsequent metastasis and drug resistance, which was also proved in other cancers." (PMID 38937712, 2024). "Secreted extracellular matrix protein, CTHRC1, may decrease collagen matrix deposition and has been linked to tumor formation, which may be one such target." (PMID 37273536, 2023). "The higher expression of CTHRC1 in tumor tissues is associated with poorer survival outcomes." (PMID 37444482, 2023). "The collagen triple helix repeat containing 1 (CTHRC1) gene encodes an extracellular matrix protein that acts as a modulator of the tumor microenvironment, and appears to be overexpressed in HNSCC tissues, as compared to healthy tissues, due to promoter hypomethylation." (PMID 36769317, 2023). "Furthermore, CTHRC1 expression has been positively associated with tumor prognosis, and it promotes invasion and metastasis by activating EMT through several signaling pathways, including the Wnt, TGF-β, and PI3K/AKT/ERK pathways." (PMID 37273536, 2023). "Previous studies indicated that high CTHRC1 expression is closely linked with tumor metastasis." (PMID 35313900, 2022). "CTHRC1 genetic alterations occur in diverse tumors and are associated with tumor progression." (PMID 34702252, 2021). "Therefore, in the current study, we aimed to examine the association of CTHRC1 expression and tumor angiogenesis and to provide more significant evidence for its application in LUAD prognosis." (PMID 31798347, 2019). "Additionally, we observed that CTHRC1 expression was positively associated with tumor angiogenesis markers, such as VEGF expression (P < 0.001) and MVD (P < 0.01)." (PMID 31798347, 2019). "CTHRC1 overexpression is reportedly associated with tumour invasion and metastasis." (PMID 29631554, 2018). "In addition, high expression of CTHRC1 was associated with advanced stage (P = 0.016) and tumor budding (P = 0.022)." (PMID 30302922, 2018). "However, the molecular mechanisms underlying tumour metastasis mediated by CTHRC1 require further investigation." (PMID 29631554, 2018). "However, the CTHRC1 expression wasn’t associated with patient’s age, tumor histological subtypes and tumor histologic grade." (PMID 29021002, 2017). "Consistent with this interpretation, our data showed that CTHRC1 expression associated with tumor angiogenesis resulted in greater infiltration of murine TEMs into the tumors, which suggests that Ang-2 regulates TEMs by the increase in blood vessels in CTHRC1-overexpressing tumors." (PMID 27686285, 2016). "Collectively, our results indicate that CTHRC1 is closely associated with tumor aggressiveness and may represent an independent prognostic biomarker for NSCLC patients." (PMID 25238260, 2014).
tumor (continued). "To minimize bias in our analysis of the association of CTHRC1 protein expression with clinicopathologic features, we used only tumor tissues for which complete clinicopathologic and long-term follow-up data were available from patients who had been operated on in the same year." (PMID 24504172, 2014). "Overexpression of CTHRC1 in HCC was associated with large tumor size and advanced tumor stage." (PMID 23922981, 2013). "Some studies indicated that the expression of CTHRC1 is also modulated by epigenetic changes, such as promoter demethylation, which can be reversed by treatment with demethylating agents, suggesting that CTHRC1’s upregulation is linked to both tumor progression and metastasis." (PMID 40978044, 2025). "Additionally, CTHRC1 overexpression induced tumor associated macrophage infiltration via AnxA1/FPR1 and GRN/TNFRSF1A signaling pathway, indicating CTHRC1 might be a promising predictive factor for immunotherapy." (PMID 37404760, 2023). "Thus, we may conclude that CTHRC1 may induce tumor associated macrophage infiltration though GRN/TNFRSF1A and AnxA1/FPR1 pathways." (PMID 35928443, 2022). "Thus, we guess that tumor-associated macrophages induced by CTHRC1 also serve as angiogenesis promoting cells via the production of pro-angiogenic factors and MMPs and also vascular construction which guarantee the supply of oxygen and nutrients to solid tumor cells." (PMID 35928443, 2022). "CTHRC1 expression at both the mRNA and protein levels is distinctly increased in multiple tumors compared with adjacent normal tissues and has been implicated in tumorigenesis and development, including tumor cell motility, proliferation, invasion, tumor lymph node metastasis, and patient prognosis." (PMID 34702252, 2021). "Furthermore, elevated preoperative serum CTHRC1 levels were associated with tumour metastasis." (PMID 29631554, 2018). "The results indicated that the expression level of CTHRC1 was closely associated with clinical stages (P = 0.0021), pathology grade (P = 0.0186), lymph metastasis (P = 0.0075), Lymphatic vascular invasion (P = 0.001), deep of invasion (P = 0.0001) and diameter of tumor (P < 0.0001)." (PMID 28303973, 2017). "It has been demonstrated that CTHRC1 facilitates tumor initiation and progression by modulating the phosphoinositide 3-kinase (PI3K)/protein kinase B (AKT) signaling pathway, thereby enhancing tumor dissemination, invasion, migration, adhesion, and metastasis." (PMID 41216505, 2026). "Multiple immunofluorescence analyses confirmed that CTHRC1 modulates immune cell infiltration and tumor cell invasion through the mediation of CAFs." (PMID 40134434, 2025). "The results demonstrated a strong positive correlation between CTHRC1 expression and tumor invasion scores specifically in TNBC." (PMID 40134434, 2025). "CTHRC1 is a secreted protein that, once released into the tumor microenvironment, influences the immune landscape by activating the STAT6 pathway in macrophages." (PMID 40330466, 2025). "CTHRC1 exhibits robust expression in various tumor types and facilitates cancer cell proliferation, invasion, and metastasis." (PMID 40134434, 2025). "Given its significant correlation with tumor aggressiveness, high CTHRC1 expression serves as a reliable predictor of poor prognosis in patients with GC, making it a valuable biomarker for early detection and a potential therapeutic target." (PMID 40978044, 2025). "Upregulated CTHRC1 enhances tumor invasion and migration via the EGFR/ERK1/2/AKT pathway and also influences immune response and angiogenesis." (PMID 40136652, 2025). "The expression of CTHRC1 in patients with TNBC gradually increases concomitantly with the progression of tumor T-stage and N-stage." (PMID 40134434, 2025). "Single-cell analysis revealed a significant positive correlation between CTHRC1 expression and tumour invasion score." (PMID 40134434, 2025).
tumor (continued). "The synergistic interplay between HPSCs and CTHRC1 drives tumor progression through ECM remodeling, metabolic reprogramming, and maintenance of immunosuppressive microenvironments." (PMID 40751418, 2025). "The expression of CTHRC1 in the tumor microenvironment, cellular differentiation, and cellular communication was systematically analyzed using single-cell data from TNBC." (PMID 40134434, 2025). "Immunofluorescence analysis of tumour and adjacent non-tumour tissues revealed a significant increase in M2 macrophage infiltration and elevated CTHRC1 expression levels." (PMID 40134434, 2025). "In conclusion, CTHRC1 plays a pivotal role in the progression and metastasis of GC, through promoting tumor invasion, regulating immune cell infiltration, and enhancing angiogenesis." (PMID 40978044, 2025). "CTHRC1 expression in HNSCC was analyzed between tumor and adjacent normal tissues, different stages were compared, and its impact on clinical prognosis was assessed using Kaplan-Meier analysis." (PMID 38937712, 2024). "High expression of CTHRC1 predicts poor prognosis and is associated with immune infiltration in HNSCC, confirming its utility as a tumor marker for HNSCC." (PMID 38937712, 2024). "Compared with the adjacent normal tissues, the expression of CTHRC1 was significantly increased in the tumor tissues with a LogFC value of 3.5." (PMID 38937712, 2024). "CTHRC1 not only interacts with the integrin β3‐Akt signaling pathway to increase myometrial invasion in the tumor microenvironment of EC but also promotes M2‐like tumor‐associated macrophage (TAM) invasion by increasing the expression of CX3CR1 in macrophages." (PMID 38466034, 2024). "Recent research has revealed that the expression of CTHRC1 is positively correlated with tumor stage and prognosis in various tumors." (PMID 38937712, 2024). "In summary, LINC00518 promotes tumor cell proliferation, migration, invasion, and clustering by regulating the downstream miR-335–3p-CTHRC1-integrin β3/FAK pathway." (PMID 39108268, 2024). "A CAF subpopulation with marked CTHRC1 expression in GC was discovered, which was overexpressed in tumor tissues compared to normal one and mediated tumor progression." (PMID 39251966, 2024). "In the present study, we found that CTHRC1 expression was significantly higher in tumor tissues consistent with lee’s study in which the HNSCC samples showed a 12.3fold higher expression than normal samples." (PMID 38937712, 2024). "Based on database analysis, we examined the correlation of CTHRC1 expression with the response to anti-tumor drugs." (PMID 39052013, 2024). "Since the ESTIMATE Score is negatively correlated with tumor purity, we infer that tumor purity is negatively correlated with CTHRC1 expression." (PMID 38937712, 2024). "Proof-of-concept experiments showed that the long-term (4-week) inhibition of CTHRC1 led to significant tumor suppression and ECM reduction, and also resulted in an unexpected shift in the CAF subtype from myCAFs to inflammatory CAFs (iCAFs)." (PMID 37444482, 2023). "In terms of the PSC function, CTHRC1 treatment markedly increased the genetic expression of tumor-promoting growth factors (EGF, HGF, and FGF by 4.9, 4.4, and 10.5 times, respectively) and cytokines (IL8 and IL10 by 3.7 and 2.9 times, respectively)." (PMID 37444482, 2023). "In both models, anti-CTHRC1 antibodies significantly suppressed tumor growth to a similar or slightly less extent than gemcitabine." (PMID 37444482, 2023). "A rapidly growing number of studies have demonstrated that CTHRC1 was highly expressed in a wide range of human solid tumors and functionally related to tumor cell proliferation, migration, invasion, metastasis, as well as tumor angiogenesis 36-39." (PMID 36923925, 2023). "In the orthotopic model, a combination of gemcitabine and anti-CTHRC1 produced the most significant tumor suppressive effects." (PMID 37444482, 2023).
tumor (continued). "In the subcutaneous model, the histochemical staining of tumor tissue samples for Ki67 and collagen showed a significant decrease in Ki67 in mice treated with gemcitabine or the anti-CTHRC1 antibody." (PMID 37444482, 2023). "Such dramatic changes explain well the potent tumor proliferation-promoting effect of PSCs in response to CTHRC1 stimulation." (PMID 37444482, 2023). "In vivo analysis showed that knocking down of CTHRC1 from CRC cell line inhibits the formation of tumor." (PMID 38304289, 2023). "This study aims to examine the influence of CTHRC1 on PSCs and to investigate the role of PSCs in the tumor-promoting effect of CTHRC1 at the molecular level." (PMID 37444482, 2023). "This was indicated by the significantly decreased Ki67 and collagen staining in tumor tissues in the anti-CTHRC1 group, compared to the control group in the subcutaneous model." (PMID 37444482, 2023). "Our in vitro studies clearly showed that CTHRC1 is a major regulatory factor of ECM-related genes when compared to well-established tumor-promoting cytokine TGF-β." (PMID 37444482, 2023). "The correlation between CTHRC1 and tumor is the most studied, followed by ADGRG2, while the correlation between CPD and LRTM2 and tumor is less studied." (PMID 37938417, 2023). "In vitro knockdown of CTHRC1 dramatically decreased the proliferation, migration, and invasion abilities of ATC cells, and in vivo studies in BALB/c nude mice confirmed that CTHRC1 knockdown significantly inhibited tumor growth." (PMID 37273536, 2023). "Compared to adjacent normal tissues, we observed that CTHRC1 was highly overexpressed in tumor sample of multiple cancers." (PMID 35928443, 2022). "Additional hub genes MMP13, SFRP4, ADAMTS16 and FNDC1 also significantly affect survival with their expression across tumour grades comparable to CTHRC1." (PMID 36190948, 2022). "Studies indicated that high CTHRC1 expression promotes the invasive and migratory abilities of tumor cells." (PMID 35313900, 2022). "Recent studies have shown that CTHRC1 can trigger tumor metastasis by promoting epithelial-mesenchymal transformation, promoting cell invasion, and inducing angiogenesis through a variety of signaling pathways." (PMID 35307012, 2022). "The pan-cancer analyses were performed to compare the expression of CTHRC1 in the tumor samples of TCGA combined with normal samples of TCGA and the Genotype-Tissue Expression (GTEx) by Wilcoxon rank sum test." (PMID 35928443, 2022). "Subsequently, the TIMER website was chosen to assess the correlation of CTHRC1 with the tumor immune cell infiltration level." (PMID 35307012, 2022). "Receiver operating characteristic curve (ROC) was used to analyze the distinguishing efficacy of CTHRC1 between tumor tissues and normal tissue." (PMID 35928443, 2022). "Collagen triple helix repeat containing-1 (CTHRC1), highly expressed in multiple human solid tumors, has been identified as a tumor associated protein." (PMID 35928443, 2022). "Further evidence demonstrated that Collagen Triple Helix Repeat Containing 1 (CTHRC1) produced by CRC cells increased tumor burden and the number of CLMs nodules in mouse models by modulating macrophage polarization to M2 phenotypes through TGF-β signaling." (PMID 36555840, 2022). "The expression of CTHRC1 under physiological conditions promotes wound healing; however, the pathological overexpression of CTHRC1 promotes tumour cell growth and invasion." (PMID 35300110, 2022). "The GSEA analysis showed that CTHRC1 was enriched in Gα signaling, GCPR ligand binding, neutrophil degranulation, interleukin signaling, and tumor-associated pathways." (PMID 35307012, 2022). "Under physiological conditions, the expression of CTHRC1 is conducive to wound healing; however, the pathological overexpression of CTHRC1 promotes tumour growth and proliferation." (PMID 35300110, 2022). "Previous studies have reported that CTHRC1 promotes tumor cell progression by affecting specific pathways in different cancer types." (PMID 35307012, 2022).